WDFY1 (WD repeat and FYVE domain containing 1)
Description:
Positively regulates TLR3- and TLR4-mediated signaling pathways by bridging the interaction between TLR3 or TLR4 and TICAM1. Promotes TLR3/4 ligand-induced activation of transcription factors IRF3 and NF-kappa-B, as well as the production of IFN-beta and inflammatory cytokines.
Synonyms: FENS-1; FENS1; KIAA1435; WDF1; ZFYVE17
Tractability: PROTAC: ubiquitination databases record sites on it; its protein half-life has been measured.
Gene: Protein-coding gene on chromosome 2 (223,855,716 to 223,945,357, reverse strand). Ensembl gene ENSG00000085449.
Subcellular location: Early endosome
Subcellular location (Human Protein Atlas): Golgi apparatus; Vesicles
Gene Ontology:
Molecular function: 1-phosphatidylinositol binding; protein binding; zinc ion binding; metal ion binding
Biological process: positive regulation of toll-like receptor 3 signaling pathway; positive regulation of toll-like receptor 4 signaling pathway
Cellular component: cytosol; early endosome; nucleus
Genetic constraint (gnomAD): Loss-of-function variants: 28 observed, 55.1 expected, observed/expected ratio (o/e) 0.51, 90% interval 0.38 to 0.7. The upper end of that interval is the gene's LOEUF score, 0.7, which puts it in group 2 of 6, group 1 being the genes least tolerant of losing a copy. Missense variants: 455 observed, 528.27 expected, observed/expected ratio (o/e) 0.86, 90% interval 0.8 to 0.93. Synonymous variants: 188 observed, 195.84 expected, observed/expected ratio (o/e) 0.96, 90% interval 0.85 to 1.08.
Homologues: Orthologues: chimpanzee WDFY1 (99% identical), macaque WDFY1 (99% identical), rabbit WDFY1 (98% identical), mouse Wdfy1 (98% identical), rat Wdfy1 (97% identical), guinea pig WDFY1 (96% identical), dog WDFY1 (95% identical), pig WDFY1 (94% identical), tropical clawed frog wdfy1 (81% identical), zebrafish wdfy1 (80% identical), Drosophila melanogaster Wdfy2 (47% identical), Caenorhabditis elegans wdfy-2 (40% identical), and 5 more. Paralogues in human: WDFY2 (61% identical), GGA3 (16% identical), GGA1 (15% identical), TOM1L2 (15% identical), GGA2 (14% identical), TOM1 (13% identical), STAM (11% identical), HGS (11% identical), TOM1L1 (10% identical), STAM2 (10% identical).
Diseases named in the same sentence as WDFY1 in open-access papers:
WDFY1 is named in the same sentence as 24 diseases in open-access papers, as found by Europe PMC text mining. Sharing a sentence is not in itself a finding about the gene and the disease. The quoted sentences say what the papers report.
Alzheimer disease (4 papers, 2014 to 2021). A progressive, neurodegenerative disease characterized by loss of function and death of nerve cells in several areas of the brain leading to loss of cognitive function such as memory and language. "Also, over-expression of WDFY1 is also associated with the senile plaque formation in Alzheimer’s disease." (PMID 27026195, 2016). "Furthermore, WDFY1 was also shown to play a role in autophagy and Wdfy1 expression is also related to mitochondrial dysfunction in Alzheimer’s disease of a mouse model." (PMID 35011620, 2021). "It has been reported that WDFY1 could be a biomarker for the phenotype severity in the AD11 mouse model of Alzheimer’s disease." (PMID 32477064, 2020). "Increased WDFY1 expression is also responsible for manifestation of Alzheimer’s disease." (PMID 27026195, 2016). "Interestingly, Wdfy1 level upregulation and Tia1 dysregulation were among the 16 most promising biomarkers that characterized the brain of mouse model of Alzheimer’s disease, with Wdfy1 showing the changes earlier than Tia1." (PMID 24659297, 2014). "Interestingly, we observed that WDFY1 protein levels were also increased in the hippocampus and dorsolateral prefrontal cortex of schizophrenic patients, but not in the hippocampus of Alzheimer’s disease patients with an associated psychotic disorder." (PMID 32477064, 2020). "In this line, WDFY1 protein levels were aberrantly upregulated in several brain regions of human post-mortem samples from patients with schizophrenia but not in samples from Alzheimer’s disease patients with psychosis." (PMID 32477064, 2020). "Accordingly, postmortem samples from schizophrenic patients but not from Alzheimer’s disease patients also display an increase of WDFY1 protein levels in the hippocampus and in the dorso-lateral prefrontal cortex, whereas in He–/– mice we found an increase of WDFY1 in the hippocampus and striatum." (PMID 32477064, 2020).
schizophrenia (3 papers, 2020 to 2025). A major psychotic disorder characterized by abnormalities in the perception or expression of reality. "A potential mechanism of the schizophrenia-like phenotype observed in He–/– mice could be the sustained increase on WDFY1 levels in different core brain regions implicated in schizophrenia." (PMID 32477064, 2020). "Furthermore, in another report the authors showed that WDFY1 could be associated with the DISC1 (from disrupted in schizophrenia 1) interactome and regulome." (PMID 32477064, 2020). "A recent study involving protein network analysis in ME3 showed the involvement of WDFY1 protein in a mouse model of schizophrenia." (PMID 37971544, 2024). "NF-κB was evaluated because the TLR3/4-dependent regulation of NF-κB is potentiated when WDFY1 is over-expressed and NF-κB is a core neuroinflammatory molecule involved in the pathogenesis of schizophrenia." (PMID 32477064, 2020). "First, we evaluated WDFY1 protein levels in the hippocampal samples and we found that WDFY1 was significantly upregulated (t46 = 2.845, p = 0.0065) in patients with schizophrenia compared to controls." (PMID 32477064, 2020). "Second, because WDFY1 is upregulated in the hippocampus and dorso-lateral prefrontal cortex of patients with schizophrenia and in the hippocampus and striatum of He–/– mice." (PMID 32477064, 2020). "Despite this poor information about the role of WDFY1 in the central nervous system, a previous report where the authors performed a transcriptome outlier analysis placed WDFY1 as a putative upregulated marker in schizophrenia." (PMID 32477064, 2020). "Since WDFY1 is up-regulated in the striatum and hippocampus of He–/– mice and in different brain regions of patients with schizophrenia, we then sought to characterize whether He–/– mice would recapitulate some of the schizophrenia-like phenotypes." (PMID 32477064, 2020). "Altogether, our data indicate that alterations involving the molecular axis Helios-WDFY1 in neurons during the development of core brain regions could be relevant for the pathophysiology of neuropsychiatric disorders such as schizophrenia." (PMID 32477064, 2020). "As we have seen increased WDFY1 protein levels in the hippocampus and striatum of He–/– mice and in the hippocampus and dorsolateral prefrontal cortex in schizophrenic post-mortem samples, we then hypothesized that pharmacological models of schizophrenia could mimic such molecular changes." (PMID 32477064, 2020). "No changes were observed in any subgroup of AD patients compared to controls indicating a possible specificity of this WDFY1 upregulation in patients with schizophrenia but not in patients with AD and psychosis." (PMID 32477064, 2020).
metastatic cancer (2 papers, 2016 to 2019). A carcinoma which has spread from the original site of growth to another anatomic site. "It was revealed that either downregulation of NRP2 or upregulation of WDFY1 can be an effective way to promote cell death in metastatic cancer." (PMID 30871059, 2019). "Thus, inhibiting NRP2 or hyper-activating WDFY1 can be an effective strategy to induce cell death in metastatic cancer." (PMID 27026195, 2016). "Furthermore, downregulation of NRP2 or upregulation of WDFY1 can promote cell death in metastatic cancer by controlling the signaling of VEGFRFs and maybe a potential target-based anticancer therapy." (PMID 30871059, 2019).
prostate carcinoma (2 papers, 2016 to 2024). A carcinoma that arises from epithelial cells of the prostate gland. "WDFY1 is a regulator of endocytic activity in breast and prostate cancer cells, and it is also associated with enhanced tumour growth and lung metastasis in a mouse model of BC." (PMID 39696397, 2024). "Here we showed that in prostate cancer cells, FAC1 was directly recruited to the WDFY1 promoter and inhibited its transcription in the presence of NRP2." (PMID 27026195, 2016).
asthma (1 paper, 2020). "In addition, two genes (ELMO2, WDFY1) were demonstrated to play roles in inflammation response of asthma." (PMID 32948203, 2020).
chronic pancreatitis (1 paper, 2022). A chronic inflammatory process causing damage and fibrosis of the pancreatic parenchyma. "High Wdfy1 expression in the brain of B6N is speculated to be related to reduced alcohol intake in B6N mice, whereas low Wdfy1 expression in the pancreas of B6J mice is associated with the progression of chronic pancreatitis in B6J mice." (PMID 36548271, 2022).
cognitive decline (1 paper, 2024). "Further study of WDFY1 and PLXNA1 in different cell types would likely shed light on the context that miR-29a acts to ameliorate cognitive decline with age." (PMID 37989983, 2024).
glioma (1 paper, 2021). A benign or malignant brain and spinal cord tumor that arises from glial cells (astrocytes, oligodendrocytes, ependymal cells). "The two most significantly regulated genes in both categories were stanniocalcin 1 (Stc1), a gene up-regulated in gliomas and WD repeat and FYVE domain-containing protein 1 (Wdfy1), a gene expressed in neural progenitors." (PMID 34394104, 2021).
inflammatory bowel disease (1 paper, 2021). A spectrum of small and large bowel inflammatory diseases of unknown etiology. "Moreover, WDFY1 protein was also detected in the colons of non-inflammatory bowel disease (IBD) controls and inflamed and non-inflamed colon section of IBD patients." (PMID 35011620, 2021).
Insulin resistance (1 paper, 2022). Increased resistance towards insulin, that is, diminished effectiveness of insulin in reducing blood glucose levels. "A previous study has reported that mice lacking nucleobindin 2 (NUCB2), a precursor of nesfatin involved in appetite regulation, exhibit insulin resistance and high Wdfy1 expression in their visceral macrophages, suggesting that Wdfy1 may be also involved in insulin signaling." (PMID 36548271, 2022).
lupus (1 paper, 2025). "Next, we evaluated the role of miR-29-3p and miR124-3p binding sites in WDFY1 expression since both miRNAs were reported to be involved in immune regulation, particularly associated with lupus and lupus nephritis, which was our research focus." (PMID 40497974, 2025). "WDFY1 expression has been associated with many diseases, including lupus." (PMID 40497974, 2025). "We recently reported a potential requirement of WDFY1 for FDC antigen processing and presentation in mice with inducible lupus." (PMID 40497974, 2025).
lupus nephritis (1 paper, 2025). Glomerulonephritis in the context of systemic lupus erythematosus. "We demonstrated here that miR-124 inhibited WDFY1 expression in mesangial cells, consistent with the report that miR-124 played an inhibitory role in renal mesangial growth and inflammation, making miR-124 an attractive diagnostic marker in lupus nephritis." (PMID 40497974, 2025). "We wondered if upregulation of WDFY1 could be induced by the IL-6-driven upregulation of Sp1 expression in the kidney of lupus nephritis mice." (PMID 40497974, 2025).
Parkinson disease (1 paper, 2021). A progressive degenerative disorder of the central nervous system characterized by loss of dopamine producing neurons in the substantia nigra and the presence of Lewy bodies in the substantia nigra and locus coeruleus. "Wdfy1 regulates neurite outgrowth and Aldh1a1 prevents neuronal degeneration in Parkinson’s disease." (PMID 34735454, 2021).
cancer (6 papers, 2016 to 2025). A tumor composed of atypical neoplastic, often pleomorphic cells that invade other tissues. "Regulation of WDFY1 transcription by NRP2 axis is a critical event in maintaining metastatic phenotype in cancer cells." (PMID 27026195, 2016). "In this study, we have delineated a novel mechanism for NRP2-mediated regulation of WDFY1 expression in cancer cells." (PMID 27026195, 2016). "Since increased expression of WDFY1 reduces the endocytic activity, maintenance of WDFY1 level is crucial in metastatic cancer cells to sustain high endocytic activity, essential for promotion of oncogenic activation and cancer cell survival." (PMID 27026195, 2016). "WDFY1 plays an important role in maintaining significant endocytic activity in cancer cells." (PMID 30871059, 2019). "Emerging studies suggested that the NRP2/WDFY1 axis was required to maintain endocytic activity in cancer cells, and therefore, therapeutic targeting of endocytosis may be an attractive strategy to selectively target cancer cells in a variety of malignancies." (PMID 36172369, 2022). "Moreover, NRP2/WDFY1 axis plays an important role in cancer cell endocytosis." (PMID 32104603, 2020). "The NRP2/WDFY1 axis may regulate cellular functions beyond cancer cells." (PMID 27026195, 2016). "In cancer cells, the expression of NRP2 is negatively correlated with WDFY1." (PMID 32104603, 2020). "Furthermore, NRP2 is required, through WDFY1 (WD-repeat and FYVE-domain-containing protein 1), to activate EGFR endocytosis in cancer cells and to maintain EGFR activities." (PMID 32766254, 2020).
tumour (4 papers, 2018 to 2025). "Several were anti-angiogenic (Agtrap, Gem, Wdfy1) or anti-apoptotic (Birc3, Mnda), as demonstrated by their association with tumour metastasis." (PMID 29447208, 2018). "Significant intron retention was visible in MYSM1, the gene encoding for a metalloprotease, and WDFY1, a gene of WD repeat and FYVE domain‐containing protein, which plays an important role in tumour development." (PMID 39212334, 2025).
neurodegenerative disease (2 papers, 2019 to 2022). A disorder of the central nervous system characterized by gradual and progressive loss of neural tissue and neurologic function. "Taken together, these studies indicated that PRDX6 inhibits neurogenesis of neural stem cells through downregulation of WDFY1-mediated TLR4 signaling pathway and suggest that the inhibitory effect of PRDX6 on neurogenesis plays a role in the development of neurodegenerative disease." (PMID 30097850, 2019).
WDFY1 also shares sentences with these, for which no sentence is quoted: autism (1 paper); colitis (1); epilepsy (1); genetic disorder (1); melanoma (1); memory impairment (1); parasite infections (1); psychosis (1).